ATM (ATM serine/threonine kinase)
Diseases named in the same sentence as ATM in open-access papers (continued):
Sharing a sentence is not in itself a finding about the gene and the disease.
breast cancer (continued). "According to the NCCN guidelines v2.2024 (27 September 2023), germline PVs in the genes ATM, BARD1, RAD51C, RAD51D, NF1, and CHEK2 confer an absolute breast cancer risk between 17% and 40%." (PMID 38893140, 2024). "Specifically, PVs in PALB2, ATM, CHEK2, RAD51C, and RAD51D are associated with increased lifetime breast cancer risk, ranging from 20% to 58%, depending on the defective gene and identified variant, while influenced by family history." (PMID 39001430, 2024). "PVs in genes with moderate penetrance, such as ATM, CHEK2, BRIP1, and PALB2, double the risk of breast cancer." (PMID 39624521, 2024). "Combined targeting of class I HDACs and ATM by SP-1-303 offers a promising therapeutic approach for treating ER+ breast cancers and supports further preclinical evaluation." (PMID 39008483, 2024). "The study will enrol women, unaffected by cancer, undergoing predictive testing at a familial cancer clinic for a pathogenic variant in a known breast cancer (BC) or ovarian cancer (OC) predisposition gene (BRCA1, BRCA2, PALB2, CHEK2, ATM, RAD51C, RAD51D)." (PMID 39107016, 2024). "Lastly, the penetrance for ATM and breast cancer was conservatively set to 0.2 based on data from multiple studies of hereditary breast cancer 10,11." (PMID 38854136, 2024). "In Asian populations, the pathogenic mutation frequency of ATM was around 1% for HBOC patients and similar frequencies were seen in unselected breast cancer patients." (PMID 39272924, 2024). "For ATM, the RR for breast cancer (2.27 in the combined analysis) was consistent with previous case-control and family-based analyses." (PMID 39209703, 2024). "Germline ATM mutations predispose patients to familial breast cancer and are associated with HRD in BRCA1/2-wild type breast cancer patients." (PMID 39334297, 2024). "CP466722 has the ability to impede ATM-dependent phosphorylation in MCF7 breast cancer cells, thereby impeding the growth of tumor cells." (PMID 38799250, 2024). "Cumulative lifetime penetrance estimates for female breast cancer are taken from the literature review performed by the All Syndromes Known to Man Evaluator28–32: 0.35 (ATM), 0.73 (BRCA1), 0.72 (BRCA2), 0.19 (CHEK2), and 0.38 (PALB2)." (PMID 38760335, 2024). "Several key initiators of the DNA damage response, including proteins, such as ataxia-telangiectasia mutated (ATM) and ATM- and Rad3-Related (ATR), are negatively regulated by ER in breast cancer." (PMID 37650943, 2023). "The BC susceptibility genes involved in breast cancer which cause moderate risk are BRIP1, CHEK2, ATM, RAD51C, and PALB2." (PMID 36873936, 2023). "Large and multiple independent epidemiological studies demonstrate association of germline variants in ATM and CHEK2 with incidence of ER+/HER2− breast cancer." (PMID 37390209, 2023). "On the other hand, ATM is a core component of the DNA repair system, and its signaling pathway is known to play a role in the development of breast cancer and other tumors." (PMID 38098507, 2023). "Among patients and the established breast cancer susceptibility genes, PTVs in BRCA2 and ATM, followed by PALB2, and BRCA1, were the most prevalent." (PMID 37790698, 2023).
breast cancer (continued). "For missense variants in aggregate, rare missense variants in specific domains in BRCA1, ATM, CHEK2, and PALB2 were significantly associated with increased risk of certain breast cancer subtypes." (PMID 37790698, 2023). "Recently, the Breast Cancer Consortium highlighted the necessity to also treat variant in other genes, including among others ATM, CHEK1, and CHEK2, in a similar manner to BRCA alterations, given their important influence on breast cancer development." (PMID 36753055, 2023). "A similar delay in the DNA damage response was reported with an STX3541 (non-steroidal 2-ME analogue) and radiation combination treatment in breast cancer cells, in which the ATM response was depressed in response to increased micronuclei formation." (PMID 36835001, 2023). "Somatic failure to activate ATM/CHK2, through loss of upstream DNA repair signaling, such as the MutL complex of the mismatch repair pathway, in ER+/HER2− breast cancer also induces resistance to standard endocrine therapies." (PMID 37390209, 2023). "This DNA damage was caused by interference with the ATM pathway and the production of ROS, which enhanced the anticancer effect of HSN in breast cancer cells." (PMID 37630393, 2023). "The ATM gene is located on chromosome 11q22-23 and is one of the most common breast cancer (BC) vulnerability genes after BRCA1/2." (PMID 38021491, 2023). "We found that CHEK2 is the only cell cycle checkpoint kinase gene that is more likely to be mutated in the germ line than somatically (threefold enrichment in ER+/HER2− breast cancer relative to ATM and >50-fold enrichment relative to ATR, P = 3.7 × 10−12)." (PMID 37390209, 2023). "Out of the 21 hereditary breast-cancer-related genes, (likely) pathogenic germline mutations were only present in CHEK2 (two patients) and ATM (one patient)." (PMID 37239898, 2023). "Dysregulation of these processes due to ATM dysfunction can contribute to breast cancer development and progression." (PMID 38327652, 2023). "Carriers of PALB2, BARD1, RAD51C, RAD51D, ATM, and CHEK2 are at higher risk of breast cancer as well." (PMID 37458761, 2023). "We report evidence of PTV association with overall breast cancer risk for BRCA2 and ATM with adjusted ORs of 9.75 (1.81-52.69 95% CI, p-value = 0.0081) and 7.61 (1.32-43.97 95% CI, p-value = 0.023)." (PMID 37790698, 2023). "Distribution of VUS in breast cancer predisposing genes were :APC:1(5.8%), ATM:2(11.7%), BRCA1:1(5.8%), BRCA2:5(29.4%), BRIP1:1(5.8%), CDKN2A:1(5.8%), CHEK2:2(11.7%), FANC1:1(5.8%), MET:1(5.8%), STK11:1(5.8%), NF2:1(5.8%)." (PMID 37277882, 2023). "The NCCN guidelines suggest surveillance for breast cancer in all female patients and recommends ovarian and pancreatic screening in ATM PV carriers with positive family histories." (PMID 37509701, 2023). "To test whether the association of CHEK2 mutation with poor outcome observed in breast cancer extends to other cancer types preferentially in women, we conducted a gender-stratified Kaplan-Meier analysis of disease-specific survival and somatic mutations in ATM and CHEK2 across solid cancers." (PMID 37390209, 2023). "We have previously shown that SIM2s is phosphorylated by ATM in response to DNA damage in breast cancer cell lines, and others have reported that ATM is activated by oxidative stress." (PMID 36966227, 2023). "It is of note that free KU is not able to sensitize cells to DOX treatment, which suggests that encapsulated ATM inhibitors play a specific and functional role in sensitizing resistant breast cancer cells to anticancer therapies." (PMID 36900267, 2023).
breast cancer (continued). "ATM now emerges as a pivotal regulator of breast cancer stem cell responses to stress signals, especially those signals that are induced by drugs used in antineoplastic treatment." (PMID 36900267, 2023). "Interestingly, the ATM PV carrier presented personal and family history strongly consistent with the typical clinical picture associated with this gene, being the patient diagnosed with pancreatic cancer in addition to gastric cancer and having a daughter with early-onset breast cancer." (PMID 37239438, 2023). "Protein truncating variants in ATM, BRCA1, BRCA2, CHEK2, and PALB2 are associated with increased breast cancer risk, but risks associated with missense variants in these genes are uncertain." (PMID 35585550, 2022). "Two of the VUS detected in the ATM gene (p.Asp44Gly, p.Glu2181Asp) were also found in breast cancer patients from Cameroon and Uganda14." (PMID 35039564, 2022). "The frequency of germline ATM PVs in breast cancer patients has been estimated to be approximately 1%, and PVs are associated with all subtypes, except triple-negative breast cancer." (PMID 35008949, 2022). "Olaparib, a poly(ADP-ribose) polymerase (PARP) inhibitor that has just been approved for use in Japan, was shown to be effective for CRPC with breast cancer 1, breast cancer 2 (BRCA2), or ATM serine/threonine kinase mutations in the PROfound trial." (PMID 35725469, 2022). "PVs of ATM and CHEK2 confers greater than 30% lifetime risk for breast cancer, but lower than that of BRCA1 and BRCA2, thus are regarded as moderate-high risk." (PMID 35323371, 2022). "On the other hand, heterozygous ATM germline PV/LPV can be found in 0.35–1% of the general population and are associated with an increased risk for breast cancer (BC) at a higher median age of onset (46.9 years)." (PMID 35320498, 2022). "The frequencies in other breast cancer susceptibility genes such as CHEK2 and ATM are lower in East Asian populations than that of European populations." (PMID 35494038, 2022). "Among those with a pathogenic variant in CHEK2, there were 50% with a family history of breast cancer in contrast to those with ATM where there were only 28.6% with a family history of breast cancer." (PMID 35040284, 2022). "This study reveals that ZEB1 is upregulated by autophosphorylation as well as by ATM hyperactivation in radioresistant breast cancer cells." (PMID 35454770, 2022). "For other germline risk variants (e.g., ATM serine/threonine kinase [ATM], partner and localizer of BRCA2 [PALB2], and checkpoint kinase 2 [CHEK2]), susceptibility to breast cancer has been estimated to account for less than 50% of cases." (PMID 35025760, 2022). "Of 28 with ATM, 28.6% had a family history of breast cancer, 3.6% had a history of breast cancer at a young age (less than age 50), 7.1% had a family history of ovarian cancer, and 25% had a family history of cancers associated with HBOC." (PMID 35040284, 2022). "Previous studies have shown that the ATM gene was disrupted in the human breast cancer cell line MCF-7." (PMID 35287310, 2022).
breast cancer (continued). "We show that the combined treatment with the EZH2 inhibitor GSK126 and the ATM inhibitor AZD1390 led to reduced colony formation, increased genotoxic stress, and apoptosis-mediated cell death in BRCA1-deficient mammary tumor cells in vitro." (PMID 35715861, 2022). "The use of genome-wide association studies (GWAS) in breast cancer families has allowed the identification of genes that are characterized by incomplete penetrance, e.g., CHEK2 and ATM." (PMID 35625741, 2022). "ATM and CHEK2 are examples of moderate-penetrance genes with lower lifetime risk of developing breast cancer as compared to the high-penetrance genes BRCA1 and BRCA2, and these moderate-penetrance genes account for around 6% of HBC." (PMID 35625741, 2022). "MUS81 silencing inactivated ATM/Chk2, thereby enhancing the sensitivity of breast cancer cell MCF-7 to cisplatin." (PMID 35910852, 2022). "PALB2 (1.2%) was the most commonly mutated gene other than BRCA1/2 in Chinese breast cancer patients, while CHEK2 (2.82%), ATM (1.06%), and PALB2 (0.87%) were the most commonly mutated genes other than BRCA1/2 in European populations." (PMID 35494038, 2022). "At least eight genes were found to be significantly associated with breast cancer risk: BRCA1 (MIM#113705), BRCA2 (MIM#600185), ATM (MIM#607585), BARD1 (MIM #601593), CHEK2 (MIM#604373), PALB2 (MIM#610355), RAD51C (MIM#602774), and RAD51D (MIM#602954)." (PMID 36139699, 2022). "Altogether, our data indicate that in breast cancer cells the ATM/ATR-CHK1 signaling pathway and DNA damage-stress response are tightly controlled at the transcriptional and post-transcriptional level by E4F1." (PMID 36012478, 2022). "In the last few years, there has been increasing interest in using blood samples to measure DNA methylation in cancer studies, with the most robust candidate genes ATM and BRCA1 showing associations between breast cancer risk and methylation changes." (PMID 36076918, 2022). "From 12,182 abstracts, 15 studies measuring gene penetrance covering 5 putative male breast cancer genes were found: ATM, BRCA1, BRCA2, CHEK2, and PALB2." (PMID 35885460, 2022). "Downregulation or mutation in genes such as ataxia-telangiectasia mutated (ATM), which are responsible for marking DNA damage as less severe, has been associated with the development of breast cancer." (PMID 35163783, 2022). "ZEB1 physically interacts with ATM in SUM159-P2 human breast cancer cells, such that ATM depletion significantly downregulates ZEB1 and checkpoint kinase 1 (CHK1) protein levels." (PMID 35454770, 2022). "The detection rate was 4.35% (n=8) for actionable breast cancer PVs (ATM=2, PALB2=4, CHEK2=1, PTEN=1)." (PMID 33758026, 2022). "It is now estimated that 10–25% of breast carcinomas are associated with HRD, due to BRCA1/2 PV, but also of other genes such as PALB2, ATM, ATR, BARD1, RAD51, BRIP1, or FANC." (PMID 35158866, 2022). "Similar results were obtained in 4T1 mouse mammary carcinoma cells following inducible ATM depletion." (PMID 35721517, 2022). "Among these, BRCA1, BRCA2, and PALB2 were still classified as high risk, and ATM, BARD1, CHEK2, and RAD51D were still classified as moderate risk breast cancer susceptibility genes in Chinese women." (PMID 34606182, 2021). "The patient in whom the pathogenic ATM variant and the BARD1 variant of uncertain significance were detected had breast cancer at the age of 39 and ovarian cancer at the age of 48." (PMID 34680878, 2021).
breast cancer (continued). "Studies suggest that patients with pathogenic mutations (such as BRCA1, BRCA2, ATM or CHEK2) are more prone to have axillary metastasis, related to their highly aggressive breast cancers." (PMID 34945851, 2021). "We found evidence of association with breast cancer risk for four genes, with estimated adjusted ORs of 5.3 [95% CI: 2.1–16.2] for BRCA1, 4.0 [95% CI: 1.9–9.1] for BRCA2, 3.4 [95% CI: 1.4–8.4] for ATM and 4.3 [95% CI: 1.0–17.0] for PALB2." (PMID 34887416, 2021). "Germline variants in ATM, BRCA1, BRCA2, CHEK2, and PALB2 were associated with a high risk of breast cancer; a more modest risk was associated with BARD1 and RAD51C." (PMID 34445631, 2021). "ATM gene has been recognized in recent years as a low penetrance breast cancer gene, which is a research goal for many studies." (PMID 33402103, 2021). "The overall pooled prevalence of ATM in patients with breast cancer was 7% (95% CI: 6−9%; I square: 93%; P: 0.00)." (PMID 34493284, 2021). "Recently published guidelines offer recommendations on the management of breast cancer in patients with germline mutations in BRCA1/2, PALB2, CHEK2 and ATM." (PMID 34422626, 2021). "In our cohort, personal and/or family history for ATM-related cancers, specifically breast cancer, pancreatic cancer, and hematologic malignancies, was found in 5/19 cases heterozygous for LOF variants (26%)." (PMID 34262154, 2021). "Most women with breast cancers had panel testing, allowing extrapolation of likely frequencies of other common familial genes (ATM, CHEK2, PALB2)." (PMID 34312777, 2021). "ATM, BARD1, CHEK2, and RAD51D were associated with a moderate risk of breast cancer with ORs ranging from 2-fold to 4-fold." (PMID 34606182, 2021). "In prior work, a mutational frequency of 0.4% was observed for ATM alterations in 7,675 BRCA1 and BRCA2-negative breast cancer patients in a Chinese population and a mutational frequency range of 0.45 to 1.0% was found in the US and Europe." (PMID 34471951, 2021). "In a single institutional review of 1185 breast cancer cases using multi-gene panel testing (MGPT), a high occurrence of bilateral tumors was observed in 26.3% of the ATM germline variant carriers and in as much as 41.2% of CHEK2 variant carriers." (PMID 35008774, 2021). "In contrast, capsaicin-induced autophagy was reported to play important roles in the DNA damage responses of breast cancer cells, activating the ATM-DNA-PKcs-PARP-1 axis to protect cells against apoptosis." (PMID 34512323, 2021). "To examine the clinical relevance of ALC1 status in the context of HRD cancers, we next examined if expression levels of ALC1, BRCA1/2, or ATM influence breast cancer survival in human patients." (PMID 33333017, 2021). "The blockade of APE1 activity by inhibitors has been demonstrated to induce lethality in breast cancer susceptibility (BRCA)- and ataxia-telangiectasia mutated (ATM)-deficient cells." (PMID 34006852, 2021). "The most important of these are the breast cancer susceptibility genes BRCA1 and BRCA2, and ATM and CHK2 are also important risk factors." (PMID 34198652, 2021). "The pooled prevalence of ATM in patients with breast cancer in several BRCA status was 7% (95% CI: 5−8%; I square: 97%; P: 0.00)." (PMID 34493284, 2021). "Ataxia-telangiectasia mutated (ATM) protein kinase regulates CXCL8 to enhance cell migration, invasion, and metastasis in breast cancer." (PMID 35011369, 2021).